RORC (RAR related orphan receptor C)
Diseases named in the same sentence as RORC in open-access papers (continued):
Sharing a sentence is not in itself a finding about the gene and the disease.
prostate carcinoma (2 papers, 2024). A carcinoma that arises from epithelial cells of the prostate gland. "In the transcriptional regulation network, TP63 and FOXO1 act as suppressors of prostate cancer lineage plasticity, whereas RORC exerts a promoting effect." (PMID 38778150, 2024). "Particularly, TFs TP63 and FOXO1 suppress and RORC drives prostate cancer lineage plasticity through the RTK/RAS pathway." (PMID 38778150, 2024). "Based on all the information presented above, TP63 and FOXO1 suppress prostate cancer lineage plasticity through the RTK/RAS pathway, whereas RORC drives prostate cancer lineage plasticity through RTK/RAS pathway." (PMID 38778150, 2024). "TP63 and FOXO1 inhibit prostate cancer lineage plasticity and RORC promotes it." (PMID 38778150, 2024). "Combining existing reports with the analysis presented in this study, it can be inferred that RORC, AR, LIN28B, IRF9, and IRF3 promoted prostate cancer lineage plasticity through the RTK/RAS pathway." (PMID 38778150, 2024). "The process of the RTK/RAS pathway driving prostate cancer lineage plasticity is a complex interplay involving multiple TFs, with TP63, FOXO1, and RORC potentially playing more crucial roles due to their relatively high activity levels." (PMID 38778150, 2024). "The CNVs and TFs, such as TP63, FOXO1, and RORC, promote the RTK/RAS pathway-driven prostate cancer lineage plasticity by upregulating the LEGs." (PMID 38778150, 2024). "RORC, AR, LIN28B, IRF9, and IRF3 exert promotive roles in prostate cancer." (PMID 38778150, 2024).
prostate tumor (2 papers, 2023 to 2024). "RORC could also be as a promising molecular target for the therapy of prostate tumor." (PMID 37430202, 2023).
sarcoidosis (2 papers, 2023). Sarcoidosis is a multisystemic disorder of unknown cause characterized by the formation of immune granulomas in involved organs. "However, the relative frequencies of CXCL8, IL1B, and M4SA1 transcripts were higher in TB samples whereas RORC mRNA was increased in the sarcoidosis samples." (PMID 38385142, 2023). "We noted similarly increased mRNA and protein expression of the master transcription factor regulating IL-17A production, RORC, in CD4+ T cells from the male compared to the female sarcoidosis patients." (PMID 36899902, 2023).
schizophrenia (2 papers, 2019 to 2026). A major psychotic disorder characterized by abnormalities in the perception or expression of reality. "The data suggest that a TBX21/RORC-defined, Th1/Th17-skewed T-cell signature may characterize a rituximab-responsive immunopsychiatric subtype of schizophrenia, in which B-cell depletion may secondarily modulate pathogenic T-cell response." (PMID 42281898, 2026).
T-cell leukemia (2 papers, 2022). A malignant disease of the T-lymphocytes in the bone marrow, thymus, and/or blood. "RORC is a regulator of the proinflammatory Th17/interleukin-17 axis in adult T-cell leukemia, and low expression of RORC was a negative prognostic indicator of KIRC in our study." (PMID 35127943, 2022).
thymoma (2 papers, 2021 to 2024). A neoplasm arising from the epithelial cells of the thymus. "Survival analysis revealed that thymoma patients with high LCK or RORC expressions had favorable clinical outcomes." (PMID 34778027, 2021).
Achalasia (1 paper, 2016). A disorder of esophageal motility characterized by the inability of the lower esophageal sphincter to relax during swallowing and by inadequate or lacking peristalsis in the lower half of the body of the esophagus. "Interestingly, in our results, IRF4 and BLIMP1 are important upstream regulators of genes down-regulated, such as XBP1, IGHM, CD79A, RORC, and IKZF2, stressing the implications of the immune-inflammation network in achalasia." (PMID 27511445, 2016).
adenoma (1 paper, 2013). A neoplasm arising from the epithelium. "In particular, adenomas with low E-cadherin expression was associated with decreased RORC expression following SA treatment and a blunted clinical response as demonstrated by attenuated IGF-1 and tumor size reduction." (PMID 23825587, 2013). "We next analyzed RORC mRNA expression in freshly prepared adenoma tissues that had been cultured in vitro and treated with octreotide." (PMID 23825587, 2013). "We found RORC to be upregulated by octreotide treatment for 24 h in the adenomas with high E-cadherin expression, while no change or a minor decrease was observed in adenomas with low E-cadherin expression." (PMID 23825587, 2013). "Finally, although we were able to detect RORC protein by western blot in some adenomas with very high total protein levels, the amount of protein was in general too low to reliably detect RORC protein expression in the in vivo adenoma as well as in the primary cultures in vitro (data not shown)." (PMID 23825587, 2013).
Arthritis (1 paper, 2021). Inflammation of a joint. "All RORC inhibitor-treated rats developed both spondylitis and arthritis versus 70% and 100%, respectively, in the vehicle-treated group." (PMID 34552583, 2021). "In terms of arthritis severity, both arthritis score (p=0.004) and hind paw swelling as assessed by plethysmometry (p=0.001) were increased upon RORC inhibition." (PMID 34552583, 2021). "The mean onset of arthritis was day 21 in RORC inhibitor vs day 33 in vehicle treated rats." (PMID 34552583, 2021). "This biological effect did not translate into clinical efficacy as RORC inhibition significantly accelerated the onset of arthritis and spondylitis, and aggravated the clinical severity of arthritis." (PMID 34552583, 2021).
bladder tumor (1 paper, 2024). "There was RORC down regulation in bladder tumor tissues, which was associated with chemo-resistance and tumor stage." (PMID 38741195, 2024). "In addition, RORC modulated bladder tumor cell proliferation, chemo-resistance, and glucose metabolism by inhibiting the PD-L1/ITGB6/STAT3 pathway." (PMID 38741195, 2024).
breast tumors (1 paper, 2024). "In contrast, CLOCK, NPAS2, CIART/CHRONO, BHLHE40, RORA, and RORC were significantly up-regulated in these breast tumors." (PMID 38319971, 2024).
cholangiocarcinoma (1 paper, 2025). A carcinoma that arises from the intrahepatic biliary tree (intrahepatic cholangiocarcinoma) or from the junction, or adjacent to the junction, of the right and left hepatic ducts (hilar cholangiocarcinoma). "Our analysis revealed that RORC amplification and elevated mRNA levels were detected in 20% of cholangiocarcinoma cases, compared to other members of the ROR family, including RORA and RORB." (PMID 41430037, 2025).
chorioamnionitis (1 paper, 2018). A morphologic finding indicating inflammation of the fetal sac membranes. "They found that at 1 week of life infants, with funisitis exposure and not chorioamnionitis exposure had increased RORC expression and RORC/FOXP3 ratio, which continued over the first 4 postnatal weeks." (PMID 30473713, 2018).
colorectal cancer (1 paper, 2024). A primary or metastatic malignant neoplasm that affects the colon or rectum. "Analysis of TGCA databases reveal that higher expressions of RORC and IL17 are associated with better prognosis in colorectal cancer patients." (PMID 39669566, 2024). "Our unbiased genomic analysis from TCGA databases revealed a positive correlation between both IL-17 and RORC and improved survival in colorectal cancer patients." (PMID 39669566, 2024). "Moreover, reduced expression of RORC and Il17A was correlated with poorer survival outcomes in colorectal cancer patients." (PMID 39669566, 2024).
conjunctivitis (1 paper, 2024). Inflammation of the conjunctiva of the eye. "In a murine model, it was discovered that the methylation of RORC regulates the changes in Th1/Th17 cells to participate in the immune response of conjunctivitis." (PMID 39295864, 2024).
depression (1 paper, 2023). "The ablation of RORC in mice lowers inflammation in autoimmune encephalomyelitis and lowers Th17 cells in the central nervous system that promote depression-like behaviors." (PMID 37851674, 2023).
endometriosis (1 paper, 2017). The growth of functional endometrial tissue in anatomic sites outside the uterine body. "IL-27 inhibits Th17 differentiation, and promotes the production of IL-10 in Th17 cells by the c-Maf/RORC/Blimp-1 complex, participating in the formation of an immune tolerance pattern in the late stage of endometriosis." (PMID 28300844, 2017).
estrogen-receptor negative breast cancer (1 paper, 2022). "Furthermore, RORC has been linked to TGF-β-induced EMT in hepatocytes during liver fibrosis, and in estrogen-receptor-negative breast cancer, and has been proposed as therapeutic target to treat these diseases." (PMID 35203668, 2022).
fungi infection (1 paper, 2023). "The results showed that T-bet and RORC expression sharply increased upon fungi infection." (PMID 37124046, 2023).
gout (1 paper, 2016). A condition characterized by painful swelling of the joints, which is caused by deposition of urate crystals. "We also observed higher mRNA levels of the Th17-specific transcription factor RORγt (RORC) in PsA SF than in OA, gout, and RA SF, supporting the involvement of Th17 and a possible link with CXCL10 in PsA." (PMID 27964744, 2016).
Hyperinsulinemia (1 paper, 2024). An increased concentration of insulin in the blood. "Accordingly, hyperinsulinemia maintained its immunosuppressive effect in CD4+ cells of the JAKi-treated patients by mitigating upregulation of the key Th1 transcription factors RORC and PRDM1, as well as the chemokine receptors CXCR3 and CCR5." (PMID 39768214, 2024).
insomnia (1 paper, 2025). A sleep disorder characterized by difficulty in falling asleep and/or remaining asleep. "Interestingly, of 554 risk loci for insomnia identified thus far, this locus is among only three loci that colocalize with CVD (pp>0.90; others include the APOE region and LINGO4/RORC)." (PMID 40176577, 2025).
leukemia (1 paper, 2024). A malignant (clonal) hematologic disorder, involving hematopoietic stem cells and characterized by the presence of primitive or atypical myeloid or lymphoid cells in the bone marrow and the blood. "When we compared our results with public patient databases, we found a moderately higher expression of RORC, gene encoding RORγ, in KMT2Ar leukemia patients." (PMID 38030791, 2024). "Indeed, increased RORC expression did not correlate with poor survival of AML patients, indicating an independent role of RORC expression level and a functional role in the upregulation of SREBP2, which is responsible for an SREBP2-specific role in leukemia development." (PMID 38030791, 2024).
lung injuries (1 paper, 2023). "Taken together, these data suggest that miR-29b-2-5p may regulate the balance of Th17/Th22 subsets during acute lung injuries by altering AhR mRNA, which thereby alters the expression of IL-22 and RORc." (PMID 36809070, 2023).
lupus nephritis (1 paper, 2024). Glomerulonephritis in the context of systemic lupus erythematosus. "Even though MX1, EGR1 and RORC were tested to be DEGs in the glomeruli and tubulointerstitium of primary lupus nephritis patients, in MRL/lpr mice, the difference was not being detected differentially." (PMID 39301055, 2024). "In the comparison of 62 subgroups, the up-regulated gene (PTPRC, MX1) and the down-regulated DEGs (EGR1, MME, RORC, ZBTB16, FKBP5) were verified to have mostly consistent change trends in all Lupus Nephritis vs. Normal Kidneys group with the results of GSE200306." (PMID 39301055, 2024).
medulloblastoma (1 paper, 2015). A malignant, invasive embryonal neoplasm arising from the cerebellum. "In addition, the mRNA levels of IL-17, IL-23 and RORC in tumor tissues and the serum concentrations of IL-17 and IL-23 protein were increased in patients with medulloblastoma." (PMID 26684834, 2015).
mesothelioma (1 paper, 2022). A usually malignant and aggressive neoplasm of the mesothelium which is often associated with exposure to asbestos. "Furthermore, RORC expression showed prognostic value in many cancers, especially in kidney renal clear cell carcinoma (KIRC), brain lower grade glioma (LGG), and mesothelioma (MESO)." (PMID 36186454, 2022).
mycobacterial infection (1 paper, 2016). "In human, RORC mutant patients showed decrease of IL‐17A expression by T cells, which resulted in increased susceptibility to mycobacterial infection with decreased anti‐mycobacterial Th1 response." (PMID 27980775, 2016). "Importance of IL‐17A in Th1‐mediated protective immunity against mycobacterial infection was also indicated in human RORC mutant patients." (PMID 27980775, 2016).
mycobacteriosis (1 paper, 2016). "Indeed, CD4 T cell responses to Mtb are contained in a CXCR3+CCR6+ Th subset, cells that produce IFNγ, IL-2 and TNFα, and a mutation leading to the loss of the CXCR3+CCR6+ lineage specific transcription factor RORC leads to mycobacteriosis." (PMID 27409590, 2016). "A recent study underlined that bi-allelic RORC loss-of-function mutations resulted in the absence of IL-17-producing T cells and defective IFNγ production by circulating γδ T cells and CD4+CCR6+CXCR3+ αβ T cells, and was associated with mycobacteriosis." (PMID 27409590, 2016).
pancreatic cancer (1 paper, 2022). "RORC has also been involved in the biology of certain cancer types, such as breast, renal, or pancreatic cancer." (PMID 35203668, 2022).
paroxysmal AF (1 paper, 2021). "In detail, the expression of BMAL1, RORC, and TIM genes was significantly lower in patients with persistent AF than in those with paroxysmal AF or no AF (persistent AF vs. paroxysmal AF and persistent AF vs. no AF, all p < 0.05)." (PMID 33430447, 2021).
preeclampsia (1 paper, 2025). Preeclampsia is a hypertensive disorder of pregnancy that is characterized by new-onset hypertension with proteinuria presenting after 20 weeks of gestation, and depending on mild or severe forms may initially present with severe headache, visual disturbances, and hyperreflexia. "Accordingly, women with preeclampsia (PE) have a higher expression of Th1/Th17 factors (T-bet, RORc) and a lower expression of Treg/Th2 factors (FoxP3, GATA-3) than in normal pregnancies." (PMID 41156157, 2025). "Our results (higher percentage of CD4+IL-17+) are consistent with reports of increased CD4+IL-17A+ cells in blood and increased RORc mRNA expression in the decidua and PBMCs in women with gestational hypertension, including preeclampsia." (PMID 41156157, 2025).
skin cutaneous melanoma (1 paper, 2023). "According to the cBioPortal and TIMER 2.0 database, the most mutated circadian genes among cutaneous melanoma patients were PER1, PER2, RORB and RORC." (PMID 37373286, 2023).
spondylitis (1 paper, 2021). The inflammation of a vertebra. "The mean onset of spondylitis was day 25 in RORC inhibitor versus day 34 in vehicle treated rats." (PMID 34552583, 2021).
steatosis (1 paper, 2021). Increased lipid within the cytoplasm of cells. "While the expression of other candidates, including RORA, RORC, and THRB, remained unchanged, that of PPARA significantly decreased as NAFLD progressed to steatosis and NASH, and showed a negative correlation with that of MIR20B." (PMID 34964438, 2021).
tumor (45 papers, 2013 to 2025). "In particular, the data on RORC gene expression in tumor and normal tissues, as well as the data showing the association between RORC expression and cancer prognosis, were obtained retrospectively from public databases." (PMID 36186454, 2022). "The synthesis of androgens by GBM cells itself may be associated with the migration of RORC-Treg cells (regulatory T cells with the related orphan receptor C) into the tumor niche and the formation of an immunosuppressive microenvironment, further facilitating tumor growth." (PMID 36361793, 2022). "Research indicated that RORC deficiency results in the aberrant expression of Th2-associated molecules, such as IL4, within Th17 cells, thereby diminishing their anti-tumor efficacy." (PMID 40436857, 2025). "RORC serves as the pivotal transcription factor essential for both the differentiation and functional maintenance of Th17 cells, exerting anti-tumor immunity through the regulation of inflammatory factor expression, including IL17A." (PMID 40436857, 2025). "Consistently, EZH2-high tumours in our cohort exhibit an IL-1β/RORC-dominated Th17 signature that likely fosters tumour progression." (PMID 41209556, 2025). "This suggested that RORC in NK cells relied on the inhibition of ferroptosis to inhibit tumor growth." (PMID 40399270, 2025). "In the clinical context, targeting RORC in BCa has the potential to modulate immune responses and inhibit tumor growth, but its variable expression in tumor subtypes complicates its universal therapeutic application." (PMID 40806474, 2025). "It was noted the RORC was significantly downregulated in tumor tissues compared to the normal tissue, while CDC6 was upregulated." (PMID 40356904, 2025). "In MM pathology, the involvement of RORC is primarily related to its role in regulating the tumor microenvironment and immune responses." (PMID 39062480, 2024). "In this study, RORC expression was evaluated in 33 cancer types and the effects of RORC on the tumor immune microenvironment were determined." (PMID 36186454, 2022). "Our study showed that there were significant differences in RORC expression between tumor and normal tissues (adjacent normal tissues [TCGA data] and healthy tissues [GTEx data]) in some cancers." (PMID 36186454, 2022). "In a small number of cancers, RORC expression was correlated with age (7/33), sex (4/33), and tumor stage (9/33)." (PMID 36186454, 2022). "We explored the differences in RORC expression between tumor and normal tissues in 33 human cancers." (PMID 36186454, 2022). "We also found that expression of RORC was comparable in tumor and normal tissues, although its expression level was significantly lower in advanced-stage tumor tissues." (PMID 35127943, 2022). "The expression levels of all genes, except RORC, showed significant differences among tumor and normal tissues." (PMID 35127943, 2022). "Univariate analysis indicated that the elevated mRNA levels of both SSTR2 and RORC were associated with a larger decrease in IGF-1 levels and tumor reduction." (PMID 23825587, 2013). "Our results indicated that single cells could be categorized into six subclusters, with tumor samples analysis revealing that RORC was predominantly expressed in epithelial cells." (PMID 41430037, 2025). "Additionally, IDH1-AS1, one of the regulatory targets of RORC, has been well investigated in tumor metabolism and immunity." (PMID 39062480, 2024). "For example, modulating RORC activity or inhibiting downstream effectors could potentially disrupt the tumor-promoting effects of the tumor microenvironment and enhance the anti-tumor immune response." (PMID 39062480, 2024). "The fact that RORC is a nuclear receptor, and that its nuclear immunostaining in GH-producing tumors is associated with SRL response, established an interesting connection that suggested a functional role of RORC in the tumor nucleus." (PMID 35203668, 2022).